SOX4 (SRY-box transcription factor 4)
Diseases named in the same sentence as SOX4 in open-access papers (continued):
Sharing a sentence is not in itself a finding about the gene and the disease.
gastric cancer (continued). "The expression of Sox4 was upregulated in gastric carcinoma patients, negatively correlated with miR-138-5p, and positively correlated with MIR4435-2HG." (PMID 34532282, 2021). "To verify the correlation of Sox4 with miR-138-5p and MIR4435-2HG, we analyzed the expression of Sox4 in gastric carcinoma patients and found that Sox4 was elevated." (PMID 34532282, 2021). "Previous studies have found that Sox4 contributes to EMT induced by TGF-β in gastric carcinoma cells." (PMID 34532282, 2021). "Mechanically, we identified that MIR4435-2HG enhanced Sox4 expression by directly interacting with miR-138-5p as a competitive endogenous RNA (ceRNA) in gastric carcinoma cells, in which Sox4 was targeted by miR-138-5p." (PMID 34532282, 2021). "circDONSON interacted with SNF2L subunit of the nucleosome-remodeling factor (NURF) complex and recruited the complex to the promoter region of SOX4 and initiates SOX4 transcription in gastric cancer." (PMID 33537235, 2020). "These lncRNAs are well studied in cancer: FENDRR for its prognostic value and its involvement in gastric cancer metastasis and CASC15 for its regulation of SOX4 in RUNX1-rearranged leukemia and harboring a risk SNP for susceptibility of neuroblastoma." (PMID 29757368, 2018). "miR-129-2 downregulates the expression of SOX4, an oncogene of the SRY-related HMGB family, and epigenetic deregulation of miR-129-2 results in overexpression of SOX4 in endometrial cancer and gastric carcinoma." (PMID 29651425, 2018). "As a target gene of miR-204, SOX4 was negatively correlated with miR-204 in tissues from gastric cancer patients." (PMID 28133610, 2017). "For further study, we analyzed the relationship between miR-204 and SOX4 levels and clinicopathological parameters in gastric cancer patients." (PMID 28133610, 2017). "Concordant with former data, miR-204 and SOX4 were statistically negatively correlated in the 54 normal gastric tissues and 54 gastric cancer tissues (P < 0.001)." (PMID 28133610, 2017). "In clinical tissue research, we determined that miR-204 was expressed much lower and SOX4 expressed much higher in gastric cancer tissues compared with normal gastric tissues." (PMID 28133610, 2017). "We also determined that SOX4 was overexpressed in human gastric cancer tissues compared with normal gastric tissues." (PMID 28133610, 2017). "We collected 54 normal gastric tissues and 54 gastric cancer tissues from patients and evaluated the expression of miR-204 and SOX4, respectively." (PMID 28133610, 2017). "For example, epigenetic repression of microRNA-129-2 has been reported to induce overexpression of SOX4 in endometrial cancer, gastric cancer and HCC." (PMID 27793005, 2016). "Down-regulation of miR-129 through methylation was correlated with upregulation of the SRY-related high-mobility group box 4 (SOX4) in gastric cancers." (PMID 24194897, 2013). "Western blot analysis also demonstrated that the expression of SOX4 was substantially increased in gastric cancer cells and tissues when compared with normal cells and tissues." (PMID 23285187, 2012). "MiR-211 inhibits cells proliferation by reducing SOX4 in gastric cancer 31 and cervical cancer." (PMID 35912006, 2022). "It has been revealed that lncRNA MIR4435-2HG may be a potential biomarker for the treatment and prognosis of liver cancer by upregulating the expression of B3GNT5 and may be a novel therapeutic target in gastric carcinoma by targeting the miR-138-5p/Sox4 axis." (PMID 35812755, 2022). "For instance, an interesting study reveals that silencing of circ-DONSON (circbase ID: hsa_circ_0004339) represses cell proliferation, migration, and invasion, and enhances apoptosis via recruiting the nucleosome remodeling factor (NURF) complex to initiate SOX4 expression in gastric cancer." (PMID 33729388, 2021).
gastric cancer (continued). "It was reported that miRNA-338-3p could directly target PREX2a, MACC1, Rab14, RAB23, IRS2, and Sox4 in ovarian cancer, gastric cancer, breast tumor, prostate cancer, non-small cell lung cancer, glioblastoma, and neuroblastoma." (PMID 33817311, 2021). "Double luciferase report experiment was conducted to test the gastric carcinoma cells transfected with miR-138-5p-mimics, and miR-138-5p could target Sox4." (PMID 34532282, 2021). "MiR-211 inhibits cell proliferation and invasion of gastric cancer by down-regulating SOX4." (PMID 31992202, 2020). "In gastric carcinoma, miR-381 inhibits Sox4, TMEM16A, and ZEB1 and suppresses metastasis." (PMID 33324542, 2020). "Associated analysis with clinicopathological parameters in gastric cancer patients showed miR-204 was associated with no lymph node metastasis and early tumor stages whereas SOX4 was associated with lymph node metastasis and advanced tumor stages." (PMID 28133610, 2017). "Our findings examined the important role of miR-204 and SOX4 played in gastric cancer, and they could be used as candidate therapeutic targets for gastric cancer therapy." (PMID 28133610, 2017). "SOX4 was also demonstrated to promote gastric cancer in several studies." (PMID 28133610, 2017). "We found miR-204 was expressed much lower and SOX4 expressed much higher in gastric cancer tissues compared with normal gastric tissues, and miR-204 was associated with no lymph node metastasis and early tumor stages whereas SOX4 was associated with lymph node metastasis and advanced tumor stages." (PMID 28133610, 2017). "Therefore, we provided new evidence that miR-204 and SOX4 can be used as new therapeutic targets for gastric cancer therapy." (PMID 28133610, 2017). "Moreover, we documented that miR-204 and SOX4 were negatively correlated in tissues from gastric cancer patients." (PMID 28133610, 2017). "MiR-129 was down-regulated and leaded to over-expression of SOX4 in primary gastric cancers." (PMID 27655675, 2016). "In prostate cancer, gastric cancer, and colon cancer, SOX4 might be used as a marker to predict the prognosis." (PMID 26578818, 2015). "Additionally, circ-DONSON might recruit the NURF complex to transcription factor SOX4 promoter and initiate its transcription, thus facilitating gastric cancer growth and invasion." (PMID 34116677, 2021). "In addition, miR-204 and SOX4 were negatively correlated in tissues from gastric cancer patients." (PMID 28133610, 2017). "Therefore, the pathway miR-204 targeting SOX4 may play a combined role in suppressing gastric cancer development and progression." (PMID 28133610, 2017). "But correlated expression of miR-204 and SOX4 in gastric cancer tissues from patients remains unknown, and it is necessary for better understanding the functions and mechanisms of miR-204 and SOX4 in gastric cancer patients." (PMID 28133610, 2017). "A study found that circFOXP1 was highly expressed in gastric cancer (GC) and demonstrated that ALKBH5-mediated m6A modification of circFOXP1 promoted GC progression by regulating SOX4 expression and sponging miR-338-3p." (PMID 38745044, 2024). "In gastric cancer, low expression of miR-140-5p can regulate the EMT regulator SOX4 to inhibit cancer cell proliferation and metastasis." (PMID 39519347, 2024). "Meanwhile, other studies affirmed that miR-138 can affect the proliferation, apoptosis, and invasion of lung, ovarian, and gastric cancer cells by targeting the expression of PD-L1, HIF-1α, SOX4, or H2AX." (PMID 35505294, 2022). "In gastric cancer, miR‐381 reverses the EMT process and thus limits the migratory and invasive capacities of gastric cancer cells by downregulating SOX4 expression." (PMID 35014178, 2022). "In gastric cancer, MIR4435-2HG has been shown to promote gastric cancer progression through the miR-497-5p/NTRK3 axis and the miR-138-5p/Sox4 axis." (PMID 35784328, 2022).
gastric cancer (continued). "Circ-DONSON promotes gastric cancer cell growth and invasion via NURF complex dependent activation of SRY-box transcription factor 4 (SOX4)." (PMID 34853591, 2021). "MIR4435-2HG is elevated in gastric carcinoma cells and contributes to the growth, metastasis, and EMT of gastric carcinoma cells by targeting miR-138-5p/Sox4 axis." (PMID 34532282, 2021). "As for miR-129-2, it has been reported to be frequently methylated in hepatocellular carcinoma and gastric cancer, and methylation-mediated repression of miR-129-2 enhanced oncogenic SOX4 expression in HCC, gastric cancer, and endometrial cancer." (PMID 25772485, 2015). "Furthermore, WB detection also confirmed that E-cadherin protein elevated while vimentin, fibronectin, and Sox4 protein declined, suggesting that MIR4435-2HG can inhibit EMT in gastric carcinoma cells by controlling miR-138-5p/Sox4 axis." (PMID 34532282, 2021). "The expression of Sox4 was positively correlated with MIR4435-2HG and negatively correlated with miR-138-5p, suggesting that MIR4435-2HG may regulate EMT in gastric carcinoma cells through miR-138-5p/Sox4 axis." (PMID 34532282, 2021). "The luciferase activity of Sox4-WT was suppressed by miR-138-5p-mimics, and qRT-PCR and WB detection revealed that Sox4 protein and mRNA in gastric carcinoma transfected with miR-138-5p-mimics were obviously inhibited in SGC-7901 and MGC-803 cells, indicating that miR-138-5p can target Sox4." (PMID 34532282, 2021). "For example, HOXA11-AS promotes gastric cancer cell growth by functioning as a ceRNA for miR-1297, while HOXD-AS1 acts as a ceRNA for miR-130a-3p and facilitates liver cancer metastasis by regulating SOX4." (PMID 31959200, 2020). "SOX4 belongs to sex-determining region Y (SRY) box family and was recently found to be an oncogene in prostate cancer, colon cancer, lung cancer, bladder cancer, gastric cancer, and so forth." (PMID 28133610, 2017). "For example, circNHSL1 served as an oncogenic circRNA in progression and metastasis of gastric cancer through the circNHSL1/miR-1306-3p/SIX1/Vimentin regulatory gene network; circDONSON promoted progression and development of GC cells via the NURF complex-dependent activation of SOX4 signaling." (PMID 32386516, 2020). "Moreover, miR-204 and SOX4 showed a negative correlation in tissues from gastric cancer patients, which indicated that the pathway miR-204 targeting SOX4 played an important role to suppress tumorigenesis and progression of gastric cancer." (PMID 28133610, 2017). "Similarly, in gastric cancer (GC), circ-DONSON recruits the NURF complex to the SOX4 promoter and initiates its transcription, thus promoting the proliferation, migration, and invasion of GC cells." (PMID 35645336, 2022).
bladder cancer (45 papers, 2008 to 2025). "The results showed that SOX4 mutations were present in several cancer types, particularly in prostate and bladder cancer, with alteration frequencies of approximately 2% and 1.2%, respectively." (PMID 34442467, 2021). "Sry-related HMG-box-4 (SOX4), a developmental transcription factor, is overexpressed in many bladder cancer patients." (PMID 40635786, 2025). "The SE-related oncogene SOX4 can either indirectly or directly suppress WNT5a levels, and WNT5a most likely protects bladder cancer cells from invasion." (PMID 37501079, 2023). "For instance, SOX4 overexpression facilitated tumor aggressiveness in bladder cancer by regulating cellular invasion via repressing WNT5a expression." (PMID 33854048, 2021). "In conclusion, we found that the expressions of circ_VANGL1 and SOX4 were enhanced, while miR-145-5p was inhibited in bladder cancer tissues and cells." (PMID 34258391, 2021). "The levels of circ_VANGL1, microRNA-145-5p (miR-145-5p), and Sex-determining region Y-related high-mobility group box 4 (SOX4) in bladder cancer tissues and cells were determined by quantitative real-time polymerase chain (RT-qPCR)." (PMID 34258391, 2021). "circ_VANGL1 mediated cell viability, apoptosis, and doxorubicin sensitivity by regulating miR-145-5p/SOX4 axis in bladder cancer, providing a potential therapeutic target for bladder cancer therapy." (PMID 34258391, 2021). "The level of circ_VANGL1 and SOX4 was increased, while miR-145-5p was decreased in bladder cancer tissues and cells." (PMID 34258391, 2021). "All data suggested that miR-145-5p regulated cell progression by affecting SOX4 in bladder cancer cells." (PMID 34258391, 2021). "SOX4 over‐expression has been studied experimentally and has been reported to be an important contributor in bladder cancer tumorigenesis." (PMID 33769711, 2021). "For example, hsa_circ_0017247 and circ-SOX4 respectively worked as tumorigenic factors in bladder cancer and non-small cell lung cancer by activating the Wnt/β-catenin signaling pathway." (PMID 33596920, 2021). "Here, we observed that SOX4 is mainly amplified in primary bladder tumors, whereas only SOX2 expression is associated with poor recurrence-free survival in patients with bladder cancer." (PMID 32427884, 2020). "SOX4 gene expression correlates with advanced cancer stages and poor survival rate in bladder cancer, supporting a potential role as a regulator of the bladder CSC properties." (PMID 30072631, 2018). "SRY-box 4 (SOX4) is often overexpressed in diverse cancers, including prostate, liver, lung, and bladder cancer, with poor prognostic features." (PMID 24551595, 2014). "It has been shown that miR-129-5p was deregulated in several tumor types including endometrial cancer, esophageal cancer, colon cancer and bladder cancer, and its verified target genes included SOX4, VCP/p97 and Cdk6." (PMID 24358111, 2013). "For some of the TFs not previously reported to be deregulated in CRC, the involvement in the tumorigenesis of other cancers has been well established for example, SOX4 in bladder cancer and CBFB in acute myeloid leukaemia." (PMID 19156145, 2009). "A recent study reported that the SOX4 expression level correlated with survival in patients with urinary bladder cancer." (PMID 19156145, 2009). "This suggests that SOX4 may regulate WNT5a levels either directly or indirectly, and WNT5a play a protective role in preventing invasion in bladder cancer cells." (PMID 40635786, 2025). "SOX4 regulates invasion of bladder cancer cells via repression of WNT5a." (PMID 38520027, 2024). "Furthermore, patients with grade 3 bladder cancer frequently expressed SOX4 at higher levels than those with lower‐grade tumours." (PMID 35522942, 2022). "Furthermore, miR-145-5p regulated SOX4 to affect cell progression in bladder cancer cells, including viability, apoptosis, and doxorubicin sensitivity." (PMID 34258391, 2021).
bladder cancer (continued). "Several reports indicated the importance of SOX4 expression in bladder cancer development." (PMID 34768751, 2021). "Moreover, our results revealed that SOX4 expression was enhanced in bladder cancer tissues and cells." (PMID 34258391, 2021). "In addition, SOX4 is overexpressed in many other types of human cancers, including leukemia, melanoma, glioblastoma, medulloblastoma, bladder cancer, and lung cancer." (PMID 34863188, 2021). "SOX4 is over expressed in several tumor types and was found to be significantly over expressed in bladder tumors in a recent investigation, suggesting a role for SOX4 in bladder cancer development." (PMID 18237450, 2008). "For example, SOX4 could modulate the invasion of bladder cancer cells by suppressing WNT5." (PMID 37251541, 2023). "Furthermore, we proposed a novel circ_VANGL1/miR-145-5p/SOX4 signaling regulatory network in bladder cancer, which might provide a potential biomarker and therapeutic target for bladder cancer." (PMID 34258391, 2021). "Besides, the expression of SOX4 in bladder cancer cells was evaluated." (PMID 34258391, 2021). "Therefore, it could be concluded that the invasion of bladder cancer cells is regulated by SOX4 through the repression of WNT5a." (PMID 34768751, 2021). "Our results suggested that lncARSR acts as a nature miRNA sponge to positively regulate SOX4 expression through sponging miR-129-5p and subsequently promotes the proliferation, migration and invasion of Bca cells, thus playing an oncogenic role in the progression of bladder cancer." (PMID 31892841, 2020). "Altogether these data suggest that SOX4 gene may have a role in bladder cancer tumorigenesis." (PMID 30072631, 2018). "NAT10 mediates ac4C modification of oncogenes (BCL9L, SOX4, and AKT1) in bladder cancer to enhance their mRNA stability, thereby promoting cancer cell malignant behaviors and stem-cell-like properties." (PMID 40999468, 2025). "In bladder cancer, NAT10 knockdown specifically attenuated mRNA ac4C modification, impairing translation efficiency of BCL9L/SOX4/AKT1 and accelerating degradation of BCL9L/SOX4 transcripts." (PMID 40881352, 2025). "For example, the expression of stem cell markers such as SOX2, IGF1R, SOX4, ALDH1, and CD44 affects the likelihood of recurrence and metastasis in bladder cancer." (PMID 41153362, 2025). "The down-regulation of NAT10 results in the reduction of ac4C modification in specific regions of mRNA, impairing translational efficiency of BCL9L, SOX4, AKT1 as well as the stability of BCL9R and SOX5, thereby reducing bladder cancer burden." (PMID 38233839, 2024). "NAT10 mediates ac4C acetylation of BCL9L, SOX4, and AKT1, enhancing their mRNA stability and promoting proliferation, migration, and stemness while inhibiting apoptosis in bladder cancer." (PMID 39640362, 2024). "For example, the SE-driven oncogenes SOX4 and EGFR participate in cell migration and invasion in bladder cancer." (PMID 37501079, 2023). "To summarise, the dynamic accommodation of BCL9L, SOX4 and AKT1 transcripts mediated by NAT10‐dependent ac4C modification is critical for the progression of bladder cancer." (PMID 35522942, 2022). "To further examine the potential of SOX2, SOX4, and IGF1R signaling in bladder cancer prognosis, we correlated the expression of these molecules with recurrence-free survival in primary bladder tumors." (PMID 32427884, 2020). "The amplicon in chromosome 6 contains SOX4 and E2F3 and is frequently found amplified in bladder cancer." (PMID 30072631, 2018). "In bladder cancers, both ID4 and SOX4 were amplified and overexpressed heterogeneously, similar to astrocytomas, and contributed to the variable biological and clinical behavior of the tumors." (PMID 23613880, 2013). "Similarly, NAT10 stabilizes BCL9L, SOX4, and AKT1 transcripts in bladder cancer through 3'UTR ac4C modification, fueling proliferation and invasion." (PMID 40588654, 2025).
bladder cancer (continued). "In this section, we utilised an animal model that is more analogous to human bladder cancer to ultimately substantiate the role of NAT10 in regulating the expression of targets such as BCL9L, SOX4 and AKT1 through ac4C modification, therefore, promoting BLCA progression." (PMID 35522942, 2022). "Kaplan-Meier analysis showed that SOX2, but not SOX4, expression correlated with a poor recurrence-free survival in bladder cancer patients, and the patients harboring a SOX2-high/SOX4-low signature had a worse recurrence-free survival outcome than those with SOX2-low/SOX4-high signature." (PMID 32427884, 2020). "The amplicon in chromosome 6 that contains SOX-4 and E2F3 is frequently found amplified in bladder cancer might be epigenetically regulated and might be a potential target for therapy." (PMID 30072631, 2018). "In addition, in bladder cancer cell J82 with down-regulated expression of CHAF1A, some down-regulated expression of several genes related to cell growth and proliferation were found, including STAT2, STAT6, AKT2, IRS1 and SOX4." (PMID 37575547, 2023). "However, the exact role of SOX4 in bladder cancer tumorigenesis had not been elucidated." (PMID 34768751, 2021). "Based on gene expression profiling, another report showed correlation of high SOX4 expression with advanced cancer stages and poor survival, supporting again a potential role of SOX4 as a regulator of the BCSC properties that may serve as a biomarker of the aggressive phenotype in bladder cancer." (PMID 30072631, 2018).